SERPIND1 (serpin family D member 1)
Diseases named in the same sentence as SERPIND1 in open-access papers (continued):
Sharing a sentence is not in itself a finding about the gene and the disease.
hepatic cirrhosis (1 paper, 2021). "Our suggested mRNA signature including CTNNB1, RhoA, SPINK1, IFITM3 and SERPIND1, alongside other platelets mRNA, can be utilized as biomarkers for comparison of hepatic cirrhosis and HCC." (PMID 34469466, 2021). "ROC curve analysis of these biomarkers showed promising diagnostic value but CTNNB1, SERPIND1 and SPINK1, with AUC as 0.94, 0.88 and 0.89, respectively, demonstrated that they have highest diagnostic ability to detect early stage HCC developing on the background of cirrhosis." (PMID 34469466, 2021). "RhoA, CTNNB1 and SPINK1 showed a significant 3.3-, 3.2- and 3.18-folds upregulation, respectively, in HCC patients compared to cirrhosis patients while IFITM3 and SERPIND1 presented a 2.24-fold change." (PMID 34469466, 2021). "A combination of CTNNB1, SERPIND1 and SPINK1 would generate an AUC of 1 which would be the ideal scenario for early-stage HCC detection when developing from cirrhosis." (PMID 34469466, 2021).
leukemia (1 paper, 2019). A malignant (clonal) hematologic disorder, involving hematopoietic stem cells and characterized by the presence of primitive or atypical myeloid or lymphoid cells in the bone marrow and the blood. "The research on SERPIND1 in cancers is limited to NSCLC and leukemia, and studies of SERPIND1 in other cancer types have not yet been conducted." (PMID 31637210, 2019).
lung adenocarcinoma (1 paper, 2022). A carcinoma that arises from the lung and is characterized by the presence of malignant glandular epithelial cells. "Finally, seven copper death genes related to lung adenocarcinoma were screened out, including ARHGEF39, EFCC1, SERPIND1, INSL4, ANLN, RHOV and CCL20." (PMID 36313444, 2022).
lymph node metastasis (1 paper, 2019). "Cox regression was used to analyze the effects of FIGO stage, SERPIND1 expression, pathological type, lymph node metastasis, degree of differentiation, and other factors on postoperative survival and recurrence." (PMID 31637210, 2019). "Meanwhile, positive and strongly positive expression rates of SERPIND1 were higher in the lymph node metastasis–positive group than in the lymph node metastasis–negative group, but the differences were not statistically significant (100 and 82.4% vs. 94.6 and 76.8%, P > 0.05 in all cases)." (PMID 31637210, 2019).
melanoma (1 paper, 2024). A malignant, usually aggressive tumor composed of atypical, neoplastic melanocytes. "Proteins (APOC4, PRG4, PLG, TNC, VWF and SERPIND1) and metabolites (lyso PC a C18:2, PC ae C44:3) previously associated with melanoma pathogenesis were identified as relevant in differentiating between disease stages." (PMID 39405606, 2024). "•Proteins linked to melanoma development (PRG4, APOC4, SERPIND1, VWF, TNC and PLG) were identified in the plasma-derived EVs of patients with melanoma." (PMID 39405606, 2024). "SERPIND1 has been identified in the circulating serum-derived EVs of patients with a prior history of melanoma." (PMID 39405606, 2024). "The combination of the identified proteomic and metabolomic datasets revealed the optimal features for differentiation were 2-proteins, VWF and SERPIND1 which classified the samples between those with metastatic and primary melanoma with 79.41 % accuracy (Acc > NIR, p = 0.049)." (PMID 39405606, 2024).
ovarian mucinous cystadenocarcinoma (1 paper, 2019). An invasive cystic adenocarcinoma arising from the ovary. "And the positive and strongly positive expression rates of SERPIND1 were higher in ovarian serous cystadenocarcinoma than in ovarian mucinous cystadenocarcinoma (97.4 and 72.7% vs. 77.8 and 44.4%, P < 0.05)." (PMID 31637210, 2019).
papillary thyroid carcinoma (1 paper, 2024). "Despite these insights, the association between SERPIND1 and thyroid cancer, particularly papillary thyroid carcinoma (PTC), remains unexplored, marking a significant gap in current thyroid cancer research." (PMID 38671425, 2024). "In our study, we identified three genes associated with SUMOylation modification—BMP8A, RGS8, and SERPIND1—as significant to the prognosis of papillary thyroid carcinoma (PTC) patients." (PMID 38671425, 2024). "Given the critical role of immune factors in the progression of papillary thyroid carcinoma (PTC), our study aimed to elucidate the correlations between BMP8A, RGS8, and SERPIND1 and immune cell infiltration." (PMID 38671425, 2024).
pulmonary TB (1 paper, 2024). "Four proteins, FCGR3B, FETUB, GGH, and SERPIND1, were present at significantly higher levels in the serum of pulmonary TB patients than both HCs and ORI cases, thereby exhibiting a high degree of specificity for TB." (PMID 38512356, 2024).
venous thromboembolism (1 paper, 2024). Occlusion of the lumen of a vein by a thrombus that has migrated from a distal site via the blood stream. "A previous study indicated an association between mutations in the SERPIND1 gene and venous thromboembolism, yet there is currently no study about SERPIND1 gene and CVT." (PMID 38886735, 2024).
cancer (9 papers, 2019 to 2024). A tumor composed of atypical neoplastic, often pleomorphic cells that invade other tissues. "Recent years have seen increasing research into the relationship between SERPIND1 and various malignant tumors." (PMID 38671425, 2024). "SERPIND1 contributes to the malignant behavior of cancer cells through involvement in diverse cellular processes." (PMID 31637210, 2019). "SERPIND1 is involved in coagulation, inflammation and cancer metastasis." (PMID 34469466, 2021). "To date, the role played by SERPIND1 in the context of cancer development remains largely unknown, particularly in NPC." (PMID 31040200, 2019). "Nevertheless, how the BRAF V600E-MAPK/ERK axis regulates SERPIND1 at the molecular level is still unknown and requires identification of key transcription factors which may act as critical regulators of BRAF V600E-MAPK/ERK-dependent gene regulation in several types of cancer." (PMID 35163468, 2022).
tumor (9 papers, 2005 to 2025). "Second, an immune-related gene prognostic signature were established via regression analysis, including 2 oncogenic genes (AGTR1, HTR3C) and 2 tumor suppressor genes (SERPIND1 and CD3E)." (PMID 38355782, 2024). "As the description above, not limited to C3, a series of complement related proteins, such as Serpind1, Cfd, C5, C1qbp, etc., were upregulated in tumor with YB1 treatment." (PMID 34489962, 2021). "Tumor growth curves showed that the growth rate of tumors that developed from the SERPIND1-overexpressing cells was significantly higher than that of the control group." (PMID 31637210, 2019). "The average tumor volume in the SERPIND1 overexpression group was ~2.69 times that of the control group." (PMID 31637210, 2019). "Therefore, it can be inferred that downregulation of BMP8A, RGS8, and SERPIND1 might lead to a shift in the immune microenvironment towards a pro-tumor state, thus facilitating the occurrence and advancement of PTC." (PMID 38671425, 2024). "Through univariate Cox regression analysis, nine genes, including 3 oncogenes (HTR3C, CRHR2 and AGTR1), 6 tumor suppressor genes (CD8A, CD3E, SERPIND1, CXCR6, BMX and CD247) were proved to be correlated with the overall survival of EC patients." (PMID 38355782, 2024). "In order to identify the key regulators in the ICD risk subgroups, first we verified the mRNA expression levels of these eight genes, and we found that only SFTPB and SERPIND1 were highly expressed in normal tissues, whereas FAM83A, FDCSP, KRT6A, RHOV and TPX2 were highly expressed in tumor tissues." (PMID 39247599, 2024).
infection (3 papers, 2014 to 2026). The state of being infected such as from the introduction of a foreign agent such as serum, vaccine, antigenic substance or organism. "In the current study, three SERPINs were differentially expressed following infection; SERPINA1 (α1–antitrypsin), SERPIND1 (heparin coagulation factor II) and SERPING1 (C1-inhibitor; C1INH)." (PMID 36088326, 2022).
cardiovascular disease (2 papers, 2023 to 2025). "By contrast, Heparin cofactor 2 (P05546, SERPIND1) is a thrombin inhibitor, and has predominantly been suggested to be protective against cardiovascular disease." (PMID 41361833, 2025).
SERPIND1 also shares sentences with these, for which no sentence is quoted: thrombophilia (6 papers); cardiomyopathy (2); Insulin resistance (2); Obesity (2); pancreatic cancer (2); Stroke (2); Arthritis (1); autism spectrum disorder (1); blood disorders (1); carotid atherosclerosis (1); cognitive decline (1); colorectal tumors (1); dementia (1); developmental delay (1); diseases of the nervous system (1); Disseminated intravascular coagulation (1); dysfibrinogenemias (1); endometrioid carcinomas (1); epilepsy (1); genetic disorders (1); glaucoma (1); heart failure (1); Hepatic steatosis (1); hepatitis C (1); hepatocellular carcinoma (1); Hyperglycemia (1); ischemic stroke (1); liver disease (1); lysosomal storage disease (1); metastatic disease (1).
A further 13 diseases each share a sentence with SERPIND1 in 1 paper.